GALC (galactosylceramidase)
Diseases named in the same sentence as GALC in open-access papers (continued):
Sharing a sentence is not in itself a finding about the gene and the disease.
multiple sclerosis (6 papers, 2018 to 2025). A progressive autoimmune disorder affecting the central nervous system resulting in demyelination. "Mutations in genes encoding sphingolipid metabolic enzymes (such as GALC) represent a major risk factor for multiple sclerosis, and alterations in sphingolipid metabolism in specific cell types contribute to myelin damage." (PMID 40552465, 2025). "Associations have been described between GALC and neurodegeneration in synucleinopathies and PD, multiple sclerosis (MS), and attention‐deficit hyperactivity disorder (ADHD)." (PMID 40391866, 2025). "Emerging evidence suggests that heterozygous GALC variants may contribute to multiple sclerosis, attention‐deficit hyperactivity disorder, and synucleinopathies." (PMID 40391866, 2025). "Recently, GALC was identified as a risk factor gene for multiple sclerosis." (PMID 36113749, 2022). "Similarly, galactocerebrosidase (GALC) mutations, causing Krabbe disease, are studied as potentially being related to neurodegeneration/multiple sclerosis and synucleopathies." (PMID 31284408, 2019). "Overall, patient blood-derived EV marker profiles were constant, but individual EV populations were significantly increased in disease compared to healthy controls, e.g. CD36+EVs in glioblastoma and GALC+EVs in multiple sclerosis." (PMID 37803478, 2023). "Two of these variants (TYK2 p.Pro1104Ala, overall MAF 4.1% in our samples; GALC p.Asp84Asp, overall MAF 3.9%) are in regions identified by our latest MS GWAS and show linkage disequilibrium with the common-variant associations we have previously reported." (PMID 30343897, 2018).
Parkinson disease (6 papers, 2018 to 2025). A progressive degenerative disorder of the central nervous system characterized by loss of dopamine producing neurons in the substantia nigra and the presence of Lewy bodies in the substantia nigra and locus coeruleus. "Functional connections between GBA and GALC are present, thus supporting a possible causative role of GALC in parkinsonism." (PMID 40391866, 2025). "Regarding the other two patients carrying known heterozygous GALC pathogenetic variants, Pt4 presented with parkinsonism accompanied by severe cognitive decline." (PMID 40391866, 2025). "In line with this, the GALC gene was found to be a disease risk locus for Parkinson disease, along with other lysosomal genes such as glucocerebrosidase (GBA)." (PMID 35789331, 2022). "Furthermore, the gene (GALC) coding for the psychosine degrading enzyme galactosylceramidase (GALC), has recently been identified as a risk loci for Parkinson’s disease." (PMID 29481565, 2018). "Carrier status for GALC mutations and prolonged exposure to increased psychosine could contribute to α-synuclein pathology, supporting psychosine metabolism by galactosylceramidase as a risk factor for Parkinson’s disease." (PMID 29481565, 2018). "Furthermore, Parkinson disease–like pathology in the neuron-specific Galc KO such as lipofuscin accumulation may provide evidence of the connection between GALC dysfunction and the pathogenic mechanism of other neurodegenerative diseases." (PMID 35789331, 2022). "A possible role of GALC in the metabolic pathways leading to parkinsonism is also suggested by the contribution of alpha‐synuclein inclusions in the pathophysiology of KD." (PMID 40391866, 2025). "However, it is unknown if changes in psychosine metabolism and GALC activity in the context of the aging human brain correlate with Parkinson’s disease." (PMID 29481565, 2018).
Ataxia (4 papers, 2016 to 2024). Ataxia refers to impaired coordination of voluntary muscle movement. "In turn, reduction or loss of GalC and sulfatides in mice could lead to faulty nodes of Ranvier causing tremors, ataxia, slow nerve conductions, and early death." (PMID 32381108, 2020). "Six of these candidate variants were located in genes related to ataxia phenotype including ATM, GALC, SPTBN2, SYNE1, and TWNK." (PMID 31455392, 2019).
glioma (4 papers, 2012 to 2023). A benign or malignant brain and spinal cord tumor that arises from glial cells (astrocytes, oligodendrocytes, ependymal cells). "Further experiments demonstrated that SATB2 is rarely expressed in glioma cells expressing the differentiation markers (GFAP, TUBB3, and GALC) in human GBMs." (PMID 33124191, 2020). "Immunofluorescence staining of glioma cells (60th generation), assessed by laser confocal microscopy, revealed the presence of IDH1R132H, A2B5, GalC, Vimentin, GFAP, and S-100 (B1-B6)." (PMID 25879429, 2015). "GFAP-Cre/RictorloxP/loxP mice developed gliomas reminiscent of human oligodendroglioma staining immunopositive for APC and GalC." (PMID 23077666, 2012). "In IDH-mutant/PM gliomas, coordinated hypermethylation in the transcription start site (TSS)/CpG island regions was observed in MO marker (GALC/O1), myelin components (MAG, MBP, MOBP, MOG), and essential regulators of the myelination program (MYRF/C11orf9 and SOX10)." (PMID 37055795, 2023). "The MO marker GALC/O1 and myelin components (e.g., MBP, MOG) were under-expressed in PM gliomas." (PMID 37055795, 2023). "Additionally, in a cell line (Ric0) derived from resected gliomas from newborn GFAP-Cre/RictorloxP/loxP mice expressed the Rictor transgene, stained positive for GalC and demonstrated hyperactivation of mTORC2 as compared to oligodendrocytes isolated from control littermates." (PMID 23077666, 2012).
melanoma (4 papers, 2023 to 2025). A malignant, usually aggressive tumor composed of atypical, neoplastic melanocytes. "A direct observation of increased prevalence of melanoma has also been previously reported in carriers of a potentially pathogenic variant of GALC." (PMID 40391866, 2025). "The results of the present work confirm and extend these findings by demonstrating that GALC overexpression increases the tumorigenic potential of both A2058 and A375 human melanoma cells harboring the tumor-driving BRAF(V600E) mutation." (PMID 37445731, 2023). "Next, RT-qPCR analysis was performed on A2058-upGALC vs. A2058-mock cells to assess the expression levels of genes encoding for various proteins up- or downregulated by GALC overexpression in BRAF-mutated melanoma cells." (PMID 37445731, 2023). "Here, in an attempt to gain further insights into the pro-oncogenic role of GALC in human melanoma, we performed the categorization of the top 200 nuclear-encoded genes whose expression is negatively correlated with GALC expression in the same TCGA Skin Cutaneous Melanoma data set." (PMID 38474307, 2024). "Overall, these data indicate for the first time that the expression of the lysosomal sphingolipid-metabolizing enzyme GALC may exert a pro-oncogenic impact on the proteomic landscape in BRAF-mutated human melanoma." (PMID 37445731, 2023). "The use of two cell lines harboring the same driver mutation appeared to be necessary given the well-known tumor heterogeneity and would have allowed us to define common and individual protein profiles modulated by GALC overexpression in BRAF-mutated human melanoma cells." (PMID 37445731, 2023). "The results of the present work extend previous observations about a pro-oncogenic role of GALC in Braf wildtype murine melanoma cells by demonstrating that GALC overexpression increases the tumorigenic potential of human melanoma cells harboring the tumor-driving BRAF(V600E) mutation." (PMID 37445731, 2023). "In addition, LC-MS/MS proteomic analysis, supported by transcriptomic data mining, indicates for the first time that GALC may exert a pro-oncogenic impact on the proteomic landscape in BRAF-mutated human melanoma cells." (PMID 37445731, 2023). "A2058 and A375 cells express intermediate levels of GALC mRNA and protein when compared to other human melanoma cell lines, being therefore suitable for assessing the impact of the upregulation of this enzyme on the biological behavior of human melanoma cells in a BRAF-mutated background." (PMID 37445731, 2023). "The results of the LC-MS/MS analysis of the cell extracts of control and GALC-overexpressing cells indicate that significant differences exist in the protein landscape expressed under identical cell culture conditions by the two melanoma cell lines that harbor the same driver mutation." (PMID 37445731, 2023). "GALC overexpression was shown to decrease ceramide levels and increase the tumorigenic activity of human melanoma A2058 cells, while GALC downregulation exerted the opposite effect." (PMID 40590240, 2025). "Accordingly, a progressive increase in GALC expression has been demonstrated from common nevi to stage IV human melanoma samples." (PMID 40590240, 2025). "In this frame, ATG4D, ATAD3A, and MRPL41 were the top three genes negatively correlated with GALC expression in the TCGA Skin Cutaneous Melanoma database." (PMID 38474307, 2024). "In keeping with these observations, GALC-silenced human melanoma A2058 cells were characterized by a decrease in their tumorigenic potential." (PMID 38474307, 2024). "Here, mining the cBioPortal for a Cancer Genomics data base identified the top 200 nuclear-encoded genes whose expression is negatively correlated with GALC expression in human melanoma." (PMID 38474307, 2024). "Such relationship was confirmed by the analysis of the proteomic data obtained by LC-MS/MS on human melanoma A2058 and A375 cell lines that had been engineered to stably overexpress human GALC by lentiviral infection." (PMID 38474307, 2024).
melanoma (continued). "The present work extends these observations and indicates that GALC exerts a significant impact on melanoma mitochondrial plasticity." (PMID 38474307, 2024). "Together, these data indicate that GALC upregulation exerts a significant impact on mitochondrial plasticity in human melanoma cells." (PMID 38474307, 2024). "Previous observations have shown that the lysosomal sphingolipid-metabolizing enzyme β-galactosylceramidase (GALC) exerts pro-oncogenic functions in melanoma." (PMID 38474307, 2024). "Among the proteins whose levels of expression were affected by GALC overexpression in melanoma cells, 25 of them were upregulated in both A2058-upGALC and A375-upGALC cells, whereas only 2 of them were downregulated in both cell types." (PMID 37445731, 2023). "Accordingly, increased levels of ceramide were observed in GALC-silenced human melanoma A2058 cells and tumor xenografts, with a consequent decrease in their tumorigenic potential." (PMID 37445731, 2023). "Further studies will be required to elucidate the impact of GALC on the rewiring of energetic metabolism in melanoma." (PMID 37445731, 2023). "Overall, this categorization analysis suggests that GALC upregulation modulates the protein landscape in melanoma cells by affecting the biological processes related to RNA metabolism and mitochondria function." (PMID 37445731, 2023). "Recent observations have shown that a progressive increase in GALC expression occurs during melanoma progression in human pathological skin specimens ranging from common nevi to stage IV melanoma." (PMID 37445731, 2023). "Interestingly, recent evidence also highlights a pro‐oncogenic role of GALC overexpression in melanoma." (PMID 40590240, 2025). "Overall, our data indicate that changes in GALC expression may exert a significant impact on mitochondrial plasticity in human melanoma cells." (PMID 38474307, 2024). "Indeed, the progression from common nevi to stage IV melanoma is accompanied by a progressive increase of GALC expression in human skin specimens as assessed by mRNA in situ hybridization." (PMID 38474307, 2024). "Together, these data suggest that a relationship may exist between GALC expression and mitochondrial function in various human cancers, including melanoma." (PMID 38474307, 2024). "Overall, our data indicate that GALC upregulation may exert a significant impact on mitochondrial plasticity in human melanoma cells." (PMID 38474307, 2024). "This might be associated with modifications in the sphingolipid landscape consequent to the increased GALC enzymatic activity in melanoma cells." (PMID 38474307, 2024). "Observations in our laboratory indicate that GALC might function as an oncogenic enzyme in human melanoma." (PMID 38474307, 2024). "Further studies will be required to assess the effect of the modulation of GALC activity on the sphingolipidome of human melanoma cells and how this, in turn, may orchestrate their transcriptomic and proteomic profiles." (PMID 37445731, 2023). "Thus, to assess the impact of GALC in human melanoma in a more relevant BRAF-mutated background, we investigated the effect of GALC overexpression on the proteomic landscape of A2058 and A375 human melanoma cells harboring the BRAF(V600E) mutation." (PMID 37445731, 2023). "Previous observations have shown that GALC may exert a pro-oncogenic role in Braf wildtype murine melanoma cells." (PMID 37445731, 2023). "Here, we extend these observations and demonstrate that GALC overexpression plays a pro-tumorigenic function on both A2058 and A375 human melanoma cells that harbor the BRAF(V600E)-activating mutation, which is present in approximately 50% of human melanomas." (PMID 37445731, 2023). "Thus, GALC appears to modulate the energetic plasticity of melanoma cells by metabolic reprogramming." (PMID 37445731, 2023). "However, the mechanism(s) by which GALC exerts its pro-tumorigenic functions in melanoma remains poorly understood." (PMID 37445731, 2023).
melanoma (continued). "A similar ceramide accumulation was observed in human melanoma cells following GALC downregulation." (PMID 37445731, 2023). "Whether and how GALC represents a key player in modulating immune responses in melanoma remains to be investigated." (PMID 37445731, 2023). "Previous observations have shown that GALC downregulation may exert profound alterations in the lipidome of murine melanoma and exert a significant increase in ceramide levels in A2058 cells." (PMID 37445731, 2023). "Previous observations have shown that GALC may exert pro-oncogenic functions in human melanoma." (PMID 38474307, 2024). "At present, we do not know whether the effects observed in BRAF-mutated human melanoma cells following GALC overexpression are due to an excess of enzyme product(s) and/or a reduction in its substrate(s)." (PMID 37445731, 2023). "Together, these data suggest that GALC may modulate the metastatic potential of melanoma cells." (PMID 37445731, 2023). "Based on this cell heterogeneity, it is not surprising that GALC overexpression exerted a different impact on the proteomic landscape of the two melanoma cell lines." (PMID 37445731, 2023).
neuropathy (4 papers, 2014 to 2025). A disorder affecting the nervous system that manifests with pain, tingling, numbness, and/or muscle weakness. "Among the three patients with known GALC monoallelic pathogenetic variants, Pts2 and 3 manifested sensory organ diseases, cancer, and neuropathy, in line with previous reports on late‐onset Krabbe patients." (PMID 40391866, 2025). "KD shares some similar features with other neuropathies and heterozygous carriers of GALC mutations are emerging with an increased risk in developing NS disorders." (PMID 36362324, 2022). "Moreover, these anti-GalC antibodies cause neuropathy in rabbits that are immunized with GalC." (PMID 24945969, 2014).
encephalitis (3 papers, 2014 to 2024). An acute inflammatory process affecting the brain parenchyma. "In children with M. pneumoniae encephalitis, intrathecal antibodies directed against galactocerebroside (GalC) were found." (PMID 27047456, 2016). "Anti-GalC antibodies have not only been detected in CSF but also in the serum of M. pneumoniae encephalitis patients, including rates from 13% (2/15) to 100% (3/3), respectively." (PMID 24945969, 2014). "In another study, it was reported that intrathecal antibodies to M. pneumoniae were found to cross-react with galactocerebroside C (GalC) in eight out of 21 (38%) of M. pneumoniae encephalitis cases." (PMID 24945969, 2014). "Moreover, anti-GalC antibodies caused demyelinating neuropathy in rabbits and have been associated with demyelination in GBS, but also in encephalitis and encephalomyelitis." (PMID 27047456, 2016). "In conclusion, while PCR and serology may be of limited value in the diagnosis of M. pneumoniae encephalitis, the detection of intrathecal antibodies to M. pneumoniae, including cross-reactive antibodies against GalC and gangliosides, may be regarded as a promising new diagnostic tool." (PMID 24945969, 2014).
lung carcinoma (3 papers, 2018 to 2025). "Does it also regulate GALC through splicing, thereby contributing to the promotion of brain metastases in lung cancer?" (PMID 40069781, 2025). "To demonstrate the role of GALC in brain metastases of lung cancer, we conducted a series of experiments." (PMID 40069781, 2025). "Downregulation of GALC gene resulted from hypermethylation of its promoter, suggesting that lung cancer tumorigenesis is due in part to epigenetic inactivation of GALC." (PMID 29773994, 2018). "Given that GALC plays an important role in brain metastasis of lung cancer, we next investigated whether RBM10 has a pro-brain metastasis function through its influence on the sphingolipid metabolic pathway." (PMID 40069781, 2025). "Through alternative splicing of GALC, RBM10, as a splicing factor, downregulates GALC expression, leading to decreased S1P concentration and subsequent inhibition of brain metastasis formation in lung cancer." (PMID 40069781, 2025).
schizophrenia (3 papers, 2016 to 2021). A major psychotic disorder characterized by abnormalities in the perception or expression of reality. "Consistent with the results from the neurodegenerative cohort, GALC activity between white and gray matter was not as disparately distributed as psychosine, reaching significance in only the schizophrenia group." (PMID 29481565, 2018).
synucleinopathies (3 papers, 2018 to 2025). "This correlation provides evidence for the first time that psychosine levels and some mutations in the GALC gene may also contribute to the distribution and/or accumulation of aberrant α-synuclein in an adult α-synucleinopathy such as PD." (PMID 29481565, 2018). "This hypothesis is endorsed by previous studies on heterozygous carriers of pathogenetic variants in the GALC gene who showed an increased risk of developing different pathological conditions, including open‐angle glaucoma, pulmonary diseases, synucleinopathies, and MS." (PMID 40391866, 2025). "However, the smaller sample size of AD patients available in this study is unable to fully exclude the possibility of GALC dysregulation playing a larger role in neurodegeneration vs specifically PD or α-synucleinopathies." (PMID 29481565, 2018). "A role for GALC in α-synucleinopathies is therefore not farfetched." (PMID 33002040, 2020).
atherosclerosis (2 papers, 2018 to 2023). A disease characterized by the build-up of fatty material and calcium deposition in the arterial wall resulting in partial or complete occlusion of the arterial lumen. "Mass spectrometry results revealed that GALC expression levels were significantly increased in patients with atherosclerosis." (PMID 37474895, 2023). "Whereas it is generally assumed that lysosomal dysfunction is a secondary event in the pathophysiology of atherosclerosis and NASH, a genome-wide association study identified polymorphisms in the gene encoding the lysosomal enzyme galactocerebrosidase (GALC) in MS patients." (PMID 30454040, 2018).
colorectal cancer (2 papers, 2023 to 2025). A primary or metastatic malignant neoplasm that affects the colon or rectum. "In colorectal cancer, an increase in KHDC4 was associated with GALC expression in patients treated with oxaliplatin and capecitabine." (PMID 40560737, 2025).